RAB13 (RAB13, member RAS oncogene family)
Description:
The small GTPases Rab are key regulators of intracellular membrane trafficking, from the formation of transport vesicles to their fusion with membranes. Rabs cycle between an inactive GDP-bound form and an active GTP-bound form that is able to recruit to membranes different sets of downstream effectors directly responsible for vesicle formation, movement, tethering and fusion. RAB13 is involved in endocytic recycling and regulates the transport to the plasma membrane of transmembrane proteins like the tight junction protein OCLN/occludin. Thereby, it regulates the assembly and the activity of tight junctions. Moreover, it may also regulate tight junction assembly by activating the PKA signaling pathway and by reorganizing the actin cytoskeleton through the activation of the downstream effectors PRKACA and MICALL2 respectively. Through its role in tight junction assembly, may play a role in the establishment of Sertoli cell barrier. Plays also a role in angiogenesis through regulation of endothelial cells chemotaxis. Also involved in neurite outgrowth. Has also been proposed to play a role in post-Golgi membrane trafficking from the TGN to the recycling endosome. Finally, it has been involved in insulin-induced transport to the plasma membrane of the glucose transporter GLUT4 and therefore may play a role in glucose homeostasis.
Synonyms: GIG4
Tractability: Antibody: UniProt places it where antibodies can reach, with high confidence; its Gene Ontology location is reachable by antibodies, with high confidence; the Human Protein Atlas places it where antibodies can reach. PROTAC: UniProt records ubiquitination sites on it; ubiquitination databases record sites on it; its protein half-life has been measured.
Gene: Protein-coding gene on chromosome 1 (153,981,617 to 153,986,377, reverse strand). Ensembl gene ENSG00000143545.
Subcellular location: Cell membrane; Cytoplasmic vesicle membrane; Cell junction, tight junction; Golgi apparatus, trans-Golgi network membrane; Recycling endosome membrane; Cell projection, lamellipodium
Subcellular location (Human Protein Atlas): Cytosol; Plasma membrane
Pathways (Reactome):
Vesicle-mediated transport: RAB GEFs exchange GTP for GDP on RABs; Translocation of SLC2A4 (GLUT4) to the plasma membrane
Metabolism of proteins: RAB geranylgeranylation
Gene Ontology:
Molecular function: cAMP-dependent protein kinase inhibitor activity; G protein activity; GTP binding; GTPase activity; protein binding
Biological process: bicellular tight junction assembly; endocytic recycling; endosomal transport; Golgi to plasma membrane transport; negative regulation of cAMP/PKA signal transduction; neuron projection development; protein localization to plasma membrane; cellular response to insulin stimulus; cortical actin cytoskeleton organization; endothelial cell chemotaxis; establishment of Sertoli cell barrier; exocytosis; trans-Golgi network to recycling endosome transport; intracellular protein localization; localization within membrane; protein localization to cell leading edge
Cellular component: bicellular tight junction; cytoplasmic vesicle; cytoplasmic vesicle membrane; cytosol; endocytic vesicle; extracellular exosome; Golgi apparatus; lateral plasma membrane; neuron projection; plasma membrane; recycling endosome; recycling endosome membrane; trans-Golgi network; cell junction; endosome; insulin-responsive compartment; lamellipodium; synaptic vesicle; trans-Golgi network transport vesicle; cell-cell junction
Genetic constraint (gnomAD): Loss-of-function variants: 16 observed, 31.46 expected, observed/expected ratio (o/e) 0.51, 90% interval 0.34 to 0.77. The upper end of that interval is the gene's LOEUF score, 0.77, which puts it in group 3 of 6, group 1 being the genes least tolerant of losing a copy. Missense variants: 186 observed, 264.81 expected, observed/expected ratio (o/e) 0.7, 90% interval 0.62 to 0.79. Synonymous variants: 82 observed, 94.88 expected, observed/expected ratio (o/e) 0.86, 90% interval 0.72 to 1.04.
Homologues: Orthologues: chimpanzee RAB13 (100% identical), pig RAB13 (99% identical), dog RAB13 (95% identical), rat Rab13 (93% identical), mouse Rab13 (92% identical), guinea pig RAB13 (91% identical), macaque RAB13 (91% identical), rabbit RAB13 (87% identical), tropical clawed frog rab13 (80% identical), zebrafish rab13 (78% identical), Caenorhabditis elegans rabr-1 (41% identical). Paralogues in human: RAB8B (66% identical), RAB8A (62% identical), RAB10 (61% identical), RAB1A (50% identical), RAB1B (50% identical), RAB35 (48% identical), RAB12 (47% identical), RAB3B (47% identical), RAB3C (47% identical), RAB3A (46% identical), RAB26 (46% identical), RAB15 (45% identical), and 56 more.
Diseases named in the same sentence as RAB13 in open-access papers:
RAB13 is named in the same sentence as 36 diseases in open-access papers, as found by Europe PMC text mining. Sharing a sentence is not in itself a finding about the gene and the disease. The quoted sentences say what the papers report.
breast carcinoma (5 papers, 2020 to 2024). "β1-integrin has been linked to the tumorigenic properties of EGFR in both lung and breast cancer and Rab13 may mediate this interaction, both intra- and extracellularly." (PMID 32978434, 2020). "In addition, by influencing the tumor microenvironment, RAB13 maintains breast cancer stem cells." (PMID 37803063, 2023). "The findings demonstrated that, in comparison to normal tissues, the expression of RAB13's total protein was considerably higher in tumor tissues from the HNSC, LIHC, LUAD, UCEC and breast cancer (all P < 0.05)." (PMID 37803063, 2023).
colorectal cancer (5 papers, 2020 to 2024). A primary or metastatic malignant neoplasm that affects the colon or rectum. "Rab13 is proposed to mediate β1‐integrin exocytosis in KRAS‐dependent manner in colorectal cancer cells." (PMID 34401050, 2021). "Together, these results suggest that Rab13 regulates anchorage-independent and 3D growth through regulation of sEV secretion, linking sEV biogenesis and tumorigenesis in colorectal cancer." (PMID 32978434, 2020). "We previously showed that mutant KRAS colorectal cancer (CRC) cells release sEVs containing Rab13 protein and mRNA." (PMID 32978434, 2020). "Further understanding of how KRAS activation drives Rab13-dependent EV secretion is required to determine the cellular contexts in which these EVs are regulated and released, and whether the affects we observe extend beyond colorectal cancer." (PMID 32978434, 2020). "Similar enrichment of RAB13 has been reported in EVs derived from osteoblasts and colorectal cancer cell lines, albeit without a focus on purified sEVs9,10." (PMID 37833373, 2023).
glioma (4 papers, 2021 to 2023). A benign or malignant brain and spinal cord tumor that arises from glial cells (astrocytes, oligodendrocytes, ependymal cells). "Each glioma patient was assigned a risk score according to the following formula: risk score = (0.2433)*RAB13 + (0.4201)*LYPLA1 + (0.0013)*GAS1 + (−0.0463)*VAMP2 + (0.5165)*CNIH4 + (0.3109)*PICK1 + (−0.0864)*RAB6B + (0.0978)*GOLT1." (PMID 37062068, 2023). "Among them, Ras-related protein 13 (RAB13) is overexpressed in patients with glioma, especially in HGG, and it was also correlated with poor survival." (PMID 37242681, 2023). "We further confirmed these results with Western blotting; the protein expression of RAB13 also decreased in both the glioma cell lines." (PMID 34141710, 2021). "This novel information should help design future studies to further explore the role of miR-2276-5p and its target RAB13 in glioma progression, with the aim to exploit this knowledge for development of targeted therapies against GBM." (PMID 34141710, 2021). "The two positive autophagy regulators ZFP36L2 and RAB13 in Low‐grade Glioma patients were discovered by SNF method and Lasso method, and it was demonstrated that gallic acid can negatively regulate autophagy by inhibiting RAB13 for future LGG therapeutics." (PMID 34632655, 2021). "RAB13 was identified as the target of miR-2276-5p which was high in glioma patients, especially those with higher tumor grades and correlated with poor survival." (PMID 34141710, 2021). "To better understand which genes are the targets of miR-2276-5p in glioma, we used mirDIP, mirtargetbase, and TargetScan to predict the target genes and found that RAB13 and PLEKHG48 might be the target of miR-2276-5p." (PMID 34141710, 2021). "Additionally, we found, using bioinformatic tools, that RAB13 is differentially expressed in patients with glioma, and predicted and verified it as a target of miR-2276-5p." (PMID 34141710, 2021). "Therefore, we infer that the low expression of miR-2276-5p leads to the differential expression of RAB13, and RAB13 may promote glioma angiogenesis through the JAK/STAT3 signaling pathway, leading to tumor proliferation and poor prognosis." (PMID 34141710, 2021). "Moreover, we conclude that miR-2276-5p is likely to target RAB13 and inhibit glioma cell growth." (PMID 34141710, 2021). "Thus, we conclude that RAB13 is a genuine target of miR-2276-5p, which is differentially expressed in glioma patients, relative to the controls, as well as in LGG vs. HGG patients, making it a putative indicator to predict the prognosis of glioma patients." (PMID 34141710, 2021). "We transfected miR-2276-5p mimics and negative control (NC) miRNA into the LN229 and U87 human glioma cell lines and found that when miR-2276-5p was ectopically highly expressed in LN229 and U87 glioma cells, the expression of RAB13 mRNA in cells was decreased, as evaluated by RT-PCR." (PMID 34141710, 2021).
glioblastoma (3 papers, 2009 to 2024). The most malignant astrocytic tumor (WHO grade IV). "Other genes hypomethylated and overexpressed in PTCL - RAB13, MPZL1, CDK14- were implicated in tumor progression of several different tumors including B-cell lymphomas, and glioblastomas, lung and ovarian." (PMID 38464090, 2024). "Using RT-PCR, we confirmed that among the microvesicular transcripts shared by SW480 and glioblastoma microvesicles but not detected in mast cell microvesicles, RAB13, CXCR4, MYC, and FAS transcripts were present in the SW480-derived microvesicles." (PMID 19930720, 2009).
hepatocellular carcinoma (3 papers, 2023 to 2024). A malignant tumor that arises from hepatocytes. "RAB13’s expression has been reported to be aberrant in many cancers, including hepatocellular carcinoma and gastric cancer, but there is rare study on the RAB13 expression and clinical significance in CRC patients." (PMID 39192986, 2024). "The mechanism of RAB13 in hepatocellular cancer was also briefly investigated by us using gene set enrichment analysis (GSEA)." (PMID 37803063, 2023).
osteosarcoma (3 papers, 2022 to 2025). A usually aggressive malignant bone-forming mesenchymal neoplasm, predominantly affecting adolescents and young adults. "RAB13 is a key promoter of cellular migration and invasion, and MYOSLID upregulates RAB13 by inhibiting miR-1286 activity, thereby enhancing the metastatic potential of osteosarcoma (OS) cells." (PMID 40149492, 2025). "MYOSLID-mediated overexpression of RAB13 further drives migration and invasion in osteosarcoma cells, highlighting its oncogenic role." (PMID 40149492, 2025). "MYOSLID promotes the progression of osteosarcoma through the miR-1286/RAB13 axis, and MYOSLID plays a key role in stomach neoplasm through the miR-29c-3p-mcl-1 axis, but it has not been reported in CC." (PMID 35087586, 2022). "MYOSLID is involved in the advancement of head and neck squamous cell carcinomas (HNSCC) and osteosarcoma, and its mechanism of action is by promoting RAB13 expression by sponging microRNA-1286 or promoting invasion and metastases by regulating a part of the epithelial-mesenchymal transformation." (PMID 36280825, 2022).
Sepsis (3 papers, 2024 to 2025). Sepsis is defined as life-threatening organ dysfunction caused by a dysregulated host response to infection. "Our study revealed that elevated RAB13 expression associated with increased mortality and incidence of sepsis." (PMID 40909263, 2025). "RAB13 expression is upregulated in sepsis and positively associated with disease severity." (PMID 40909263, 2025). "Six core genes, ELANE, IL1R2, RAB13, RNASE3, FCGR1A, and TLR5, have been linked to sepsis prognosis." (PMID 39655195, 2024). "In the sepsis group, FCGR1A and TLR5 were positively associated with survival compared to ELANE, IL1R2, RAB13, and RNASE3, which were adversely associated with survival." (PMID 39655195, 2024). "SRSF7, E2F2, RAB13, and S100A8 were identified as potential pathogenic biomarkers of sepsis." (PMID 40909263, 2025). "RT-qPCR revealed decreased SRSF7 expression and increased RAB13, E2F2, and S100A8 expression in sepsis." (PMID 40909263, 2025). "Analysis of clinical prognostic data (dataset: GSE65682) in the context of sepsis revealed that the upregulation of ELANE, IL1R2, RAB13, and RNASE3 affected prognosis by reducing the survival rate of patients with sepsis." (PMID 39655195, 2024). "ELANE, IL1R2, RAB13, and RNASE3 promote cell death, whereas FCGR1A and TLR5 facilitate cell survival in sepsis." (PMID 39655195, 2024). "The PBMC were separated of twenty patients with sepsis and twenty healthy volunteers, we estimated the mRNA expression level of SRSF7, E2F2, RAB13 and S100A8 in PBMC via RT-qPCR, the mRNA expression level of SRSF7(p<0.0001) was lower in the patients with sepsis than healthy people." (PMID 40909263, 2025). "Importantly, our findings indicate that high expression levels of ELANE, IL1R2, RAB13, and RNASE3 promote death rates in sepsis, whereas high expression levels of FCGR1A and TLR5 improve the survival rate of patients with sepsis." (PMID 39655195, 2024). "In summary, these findings suggest that ELANE, IL1R2, RAB13, RNASE3, FCGR1A, and TLR5 may influence the prognosis of patients with sepsis and provide novel insights and potential avenues for the treatment of sepsis." (PMID 39655195, 2024). "Additionally, there was an increased expression of TLR5 and RAB13 in sepsis, although this change was not statistically significant and was not easily noticeable." (PMID 39655195, 2024).
gastric cancer (2 papers, 2024). A primary or metastatic malignant neoplasm involving the stomach. "TLR5 exacerbates airway inflammation and asthma symptoms, while RAB13 serves as a novel prognostic marker in gastric cancer." (PMID 39655195, 2024).
leukemia (2 papers, 2024). A malignant (clonal) hematologic disorder, involving hematopoietic stem cells and characterized by the presence of primitive or atypical myeloid or lymphoid cells in the bone marrow and the blood. "Several genes from this group, such as UHRF1, MPZL1, CDK14, RACGAP1, RAB13, and others have oncogenic functions in various solid tumors, leukemias, and lymphomas either predicting poor prognosis, involved in tumor migration, metastasis, or maintenance." (PMID 38464090, 2024).
ovarian carcinoma (2 papers, 2023 to 2025). A malignant neoplasm originating from the surface ovarian epithelium. "To verify the function of RAB13 in ovarian cancer, we detected the cellular phenotypic changes in OC cell lines that knocked down RAB13." (PMID 37046345, 2023).
autism (1 paper, 2013). Persistent deficits in social interaction and communication and interaction as well as a markedly restricted repertoire of activity and interest as well as repetitive patterns of behavior. "Eukaryotic translation elongation factor 1 alpha 1-autism association, Thymosin beta 4 – provides neuroprotection following traumatic brain injury, LPP-homolog – reported to promote synapse development, and Rab-13 – promotes neurite growth and development." (PMID 24363837, 2013).
bile duct cancer (1 paper, 2025). "Various RAB genes have been linked to tumors, including RAB27A, which serves as a predictive indicator for pancreatic ductal adenocarcinoma; RAB13 and RAB3D, which are elevated in pan-cancer; and RAB1A and RAB6A, which have significant functions in rectal cancer and bile duct cancer, respectively." (PMID 40177653, 2025).
brain cancer (1 paper, 2021). A primary or metastatic malignant neoplasm affecting the brain. "Therefore, we verified the relationship between the regulators and above‐mentioned autophagy‐related genes by knockdown and overexpression ZFP36L2 and RAB13 in Human Brain Cancer Cell Lines SW1088 cells." (PMID 34632655, 2021).
diabetes (1 paper, 2020). "In addition, the significant correlation was detected between Rab13 and Rab14 (r = 0.8971, p = 0.000) in the groups with diabetes (diabetic control group and diabetic OLP-treated groups), while between Rab8A and Rab13, and Rab8A and Rab14, results were not significant." (PMID 33256066, 2020). "To test this hypothesis, we investigated the effect of olive leaf polyphenols (OLP) on Rab8A, Rab13, and Rab14, as well as GLUT4 in the soleus muscle of rats with streptozotocin-induced diabetes (SZT)." (PMID 33256066, 2020). "This is the first investigation with clear evidence that the OLE, as a potential insulin stimulator, can be used for the treatment of diabetes via the improvement of intracellular GLUT4 translocation in the skeletal muscle by the activation of Rab8A and Rab13 proteins." (PMID 33256066, 2020).
Hodgkins lymphoma (1 paper, 2019). A heterogeneous group of malignant lymphoid neoplasms of B-cell origin characterized histologically by the presence of Hodgkin and Reed-Sternberg (HRS) cells in the vast majority of cases. "Interestingly, RNA profiling datasets from classic Hodgkin’s lymphoma, the HL subtype most closely associated with EBV, identify RS cell RAB13 mRNA expression." (PMID 31518366, 2019).
lung carcinoma (1 paper, 2021). "Candidate genes ACTR3, ARPC5, and HNRNPK were highly expressed in almost all types of lung cancer immune cells, while RAB13, PA2G4, and WDR12 were found to be less abundant in the majority of myeloid populations in lung cancer." (PMID 34868230, 2021).
metastatic tumors (1 paper, 2007). "As seen in invasive and metastatic tumors, MCF-7 cells highly expressed Rab13." (PMID 17883861, 2007).
pituitary adenomas (1 paper, 2025). "Additional genes—PHYHD1, LTBR, MYBPHL, C22orf42, PRR5, ANKDD1A, RAB13, CAMKV, KIFC3, WNT4, and STAT6—were implicated in the invasive behavior of non-functioning pituitary adenomas (NFPAs)." (PMID 39859246, 2025).
vitiligo (1 paper, 2023). Generalized well circumscribed patches of leukoderma that are generally distributed over symmetric body locations and is due to autoimmune destruction of melanocytes. "We noted that other genes, such as Lnc-ARRDC3-1, PLCG1, A_33_P3229958, TERM1, and RAB13, showed increased expression, whereas TM4SF19, IFI27, and IL17RB showed decreased expression in T cells from patients with vitiligo compared with the controls." (PMID 37731844, 2023).